RN7SL55P (RNA, 7SL, cytoplasmic 55, pseudogene)
Gene: Miscellaneous RNA gene on chromosome 4 (109,450,772 to 109,451,068, reverse strand). Ensembl gene ENSG00000243227.
Homologues: Orthologues: chimpanzee Metazoa_SRP (98% identical), macaque Metazoa_SRP (93% identical). Paralogues in human: RN7SL2 (80% identical), RN7SL3 (79% identical), RN7SL1 (78% identical), RN7SL126P (78% identical), RN7SL597P (78% identical), RN7SL411P (77% identical), RN7SL147P (77% identical), RN7SL278P (77% identical), RN7SL296P (77% identical), RN7SL566P (77% identical), RN7SL127P (77% identical), RN7SL678P (77% identical), and 699 more.